PTTG1 (PTTG1 regulator of sister chromatid separation, securin)
Diseases named in the same sentence as PTTG1 in open-access papers (continued):
Sharing a sentence is not in itself a finding about the gene and the disease.
breast carcinoma (continued). "Some studies have reported the role of CCNB1, CCNB2, PTTG1, RACGAP1, and UBE2C in cell cycle regulation, aggressive tumor behavior, a poor prognosis, resistance to therapy, and cancer stem cell regulation in breast cancer." (PMID 41009526, 2025). "The induction of breast cancer cells’ EMT, stemness, and also drug resistance are the other related actions of the PTTG1." (PMID 41009526, 2025). "In breast cancer, there is a positive relationship between PTTG3P and PTTG1 expression, with high expression indicating a poor prognosis." (PMID 39170694, 2024). "Nevertheless, after silencing the PTTG1 gene, the expression of the ENO1 downstream increased, thereby regulating the proliferation and apoptosis of breast cancer cells." (PMID 34504528, 2021). "The present findings revealed that PTTG1 and PTTG3 are two important genes with high expressions in breast cancer relative to normal breast cells, implying their unique roles in breast cancer progression." (PMID 33173433, 2020). "Collectively, these results illustrated a critical role of PTTG1 in MDA-MB-231 breast cell invasion and suggested that inhibition of PTTG1 expression is contributed, at least in part, to the inhibition of breast cancer invasion by simvastatin treatment." (PMID 33250768, 2020). "Our results showed that PTTG1 is highly expressed in malignant Hs578T and MDA-MB-231 breast cancer cell lines as compared with normal or less malignant breast cancer cells." (PMID 33250768, 2020). "Noticeably, PTTG1 gene, the transcriptional promoter of CDK1, was up-regulated in breast cancer; ZBTB16 gene was the transcriptional suppressor of CCNA2, and its expression was down-regulated in overlapping DEGs." (PMID 33083112, 2020). "Meanwhile, we found that overexpression of PTTG1 enhanced cell invasion in vehicle-treated MDA-MB-231 cells, and partially reversed simvastatin-mediated inhibition on breast cancer cell invasion." (PMID 33250768, 2020). "Our bioinformatics data demonstrated that among all PTTG members, PTTG1 and PTTG3 were distinctively highly expressed in breast cancer compared to normal tissues, implying their specific roles in breast cancer progression." (PMID 33173433, 2020). "Recently, PTTG1 was shown to regulate MMP-2 via direct promoter regulation, influence Rho-GEF ECT2, and be involved in the invasion and migration of breast cancer cells by promoting EMT." (PMID 26900962, 2016). "In addition, integrating pathway and gene information, we identified five (ID4, ANXA4, CXCL9, MYLK, FBXL7) and six (SQLE, E2F1, PTTG1, TSTA3, BUB1B, MAD2L1) known cancer genes significant for ovarian and breast cancer respectively." (PMID 22759382, 2012). "Therefore, PTTG1 and PTTG3 might be novel biomarkers for selecting appropriate chemotherapeutic regimens for breast cancer patients." (PMID 33173433, 2020). "By uploading PTTG1 coexpression genes from the METABRIC database into the Metacore platform, we found that cell cycle-related pathways and networks such as “the metaphase checkpoint” and “TTP metabolism pathway” played essential roles in breast cancer patients." (PMID 33173433, 2020). "Finally, we explored several potential mechanisms of PTTG3P in breast cancer, including construction of the pseudogene PTTG3P-miRNA-mRNA network, analysis of co-expressed genes, and assessment of its correlation with parental genes PTTG1 and -2." (PMID 31011629, 2019).
breast carcinoma (continued). "Previous studies suggested that UBE2C expression was accompanied by that of other biomarkers such as AZGP-1, prolactin-inducible protein, and S100A8 or with pituitary tumor-transforming 1 (PTTG1), Survivin and thymidin kinase 1, which might improve outcome prediction in breast cancer." (PMID 24699941, 2014). "Additionally, mice lacking Pttg1 developed spontaneous mammary tumors." (PMID 26320179, 2015). "The over-expressed CCNE1, CLGN, NEK2, PTTG1 and RAD51, and the under-expressed ADAMTS1, FOS, FOSB, IL6 and ZFP36 in tumor cells are examples of breast cancer genes without differential promoter methylation between normal and tumor samples." (PMID 25706888, 2015).
pituitary tumor (48 papers, 2005 to 2025). A benign or malignant neoplasm affecting the pituitary gland. "The PTTG1 also is a pituitary tumor-transforming gene that encodes a protein that acts as a transcription and a securing factor." (PMID 41009526, 2025). "Studies have demonstrated that high expression of PTTG1, the pituitary tumor transforming gene, is associated with increased T cell permeability in tumors." (PMID 39388011, 2024). "Mammalian securin which was initially isolated from rat pituitary tumor cells as pituitary tumor transforming gene 1 (PTTG1), is an oncogene and has been implicated in the development and progression of several malignancies." (PMID 35033090, 2022). "It has been reported that only nuclear PTTG1 expression is associated with an aggressive phenotype, at least in pituitary tumors." (PMID 33430117, 2021). "Previous studies indicated that PTTG1 is involved in the modulation of metastasis in human ovarian cancer, and is implicated in the regulation of senescence and growth of pituitary tumor." (PMID 27893422, 2017). "PTTG1 which resides at human chromosome 5q33.3 and encodes a securin protein, is first isolated from rat pituitary tumor cells in 1997." (PMID 27893422, 2017). "Pituitary tumor transforming gene 1 (PTTG1), which encodes the mammalian protein securin, was originally isolated from rat pituitary tumor cells and was then identified as a member of the securin proteins family." (PMID 27058238, 2016). "Deregulation of the pituitary tumor transforming gene (PTTG1), a newly discovered oncogene, is a hallmark of various malignancies, including pituitary tumors." (PMID 26320179, 2015). "PTTG1 has been implicated in mediating oncogene-induced pituitary tumor senescence." (PMID 21858218, 2011). "Among these three homologous genes, PTTG1 has undergone extensive investigation and has been established as closely linked to the onset and progression of various human cancer types, including pituitary tumors, gliomas, breast, thyroid, bladder, ovarian, and prostate cancers." (PMID 40877987, 2025). "Intriguingly, the oncogene pituitary tumor-transforming gene 1 (PTTG1), first identified in pituitary tumors in rats, is expressed in nearly 90% of NFPA cases." (PMID 39006628, 2024). "At the same time, there are reports that E2F1 can enhance the expression of PTTG1 in pituitary tumors, glioma, and adrenocortical carcinoma." (PMID 35210406, 2022). "PTTG1, also named tumor-transforming protein 1, was first isolated from rat pituitary tumor cells by Pei and Melmed in 1997." (PMID 35805898, 2022). "PTTG1 is a recently identified oncogene in pituitary tumors and high expression levels of PTTG1 were reported in several different cancers." (PMID 33498448, 2021). "Pituitary tumor transforming 1 (Pttg1) was originally cloned from rat pituitary tumor cells and was reported to function as an oncogene." (PMID 34307396, 2021). "A meta-analysis has confirmed increased PTTG1 expression in invasive pituitary tumors (this has also been replicated in NFPTs)." (PMID 32201880, 2020). "Pttg1 was originally described as an oncogene in pituitary tumors and found to regulate sister chromatid adhesion in M-phase of cell cycle." (PMID 33173537, 2020). "PTTG1 is upregulated in pituitary tumors; in contrast, the levels of microRNA-655, miR-300, miR-381, and miR-329 are decreased in pituitary tumor tissues." (PMID 33324542, 2020). "Human PTTG1 is an oncoprotein found in pituitary tumors and later identified as securin, a protein isolated from yeast with a reported role in chromosome separation." (PMID 30259712, 2018). "Securin, the protein product of PTTG1, in turn, is a proto-oncogene first described in rat pituitary tumour cells." (PMID 29078751, 2017).
pituitary tumor (continued). "Nevertheless, the upstream and downstream regulatory mechanisms of PTTG1 in pituitary tumors remain to be explored." (PMID 26320179, 2015). "The Western blotting and immunohistochemical results show that PTTG1 decreased from group 1 to group 6, which suggests that these miRNAs inhibit pituitary tumor cell growth though regulating PTTG1." (PMID 26320179, 2015). "PTTG1 is overexpressed in nearly all pituitary adenomas, especially in invasive hormone-secreting pituitary tumors." (PMID 25136513, 2014). "PTTG1 (pituitary tumor transforming gene), originally isolated from rat pituitary tumor cells, is a securin protein abundantly expressed in hematopoietic, colorectal, thyroid, lung, breast and ovarian malignancies." (PMID 21858218, 2011). "Further supporting this idea, high expression levels of PTTG1 have a positive correlation with increased tumor invasiveness in human pituitary tumors and degree of malignancy, pathogenesis, and progression of colorectal, thyroid, and breast tumors." (PMID 19014669, 2008). "Pituitary tumor transforming gene (PTTG1) was isolated from a pituitary tumor cell line and its over-expression results in cellular transformation in vitro and tumor formation in nude mice." (PMID 17662127, 2007). "Pituitary tumor transforming gene 1 (PTTG1), a recently characterized oncogene, was initially identified on analysis of a rat pituitary tumor; subsequently, a human homologue of PTTG1 was cloned by us and others." (PMID 15649325, 2005). "PTTG1 is the transforming gene initially found in rat pituitary tumor cells." (PMID 34025420, 2021). "Moreover, the observed shift to a pronounced nuclear localization in ISCC confirms a previous observation in aggressive-invasive subtypes of pituitary tumors (prolactin) that suggest a crucial role for PTTG1 during squamous carcinogenesis." (PMID 28073359, 2017). "With regard to the pituitary tumor transforming gene PTTG1 a functional role as an oncogene by regulating cell-cycle progression, apoptosis, cellular transformation and the tumor microenvironment in terms of increasing the expression of proangiogenic factors has been well established." (PMID 26894859, 2016). "In our study, we reveal that PTTG1 is a direct target of miR-329, miR-381, miR-300 and miR-655, which may have an oncogenic role in miRNA-induced pituitary tumor progress inhibition." (PMID 26320179, 2015). "Our results suggest that restoring PTTG1-targeting miRNAs using mimetics may have therapeutic potential for the treatment of pituitary tumors." (PMID 26320179, 2015). "On the contrary, PTTG1 deletion diminishes pituitary-tumor development in Rb heterozygous mice." (PMID 25136513, 2014). "Increased PTTG1 mRNA expression in pituitary tumor tissue has been confirmed in several studies." (PMID 21439054, 2011). "PTTG1 seems to promote pituitary tumor formation through a variety of other ways." (PMID 21439054, 2011).
pituitary tumor (continued). "Hence, PTTG1 is regarded as an oncogene for pituitary tumors and other neoplasia." (PMID 30853662, 2019). "To elucidate whether the inhibition of pituitary tumor malignant behavior by the 14q32.31 miRNAs was mediated by PTTG1, we examined the interaction between miR-329, miR-300, miR-381 and miR-655 and the mRNA of PTTG1." (PMID 26320179, 2015). "These investigators also reported the nuclear localization of PTTG1-EGFP in other cell lines like NIH3T3, rat GH3, mouse AtT20 pituitary tumor, SKOV-3 human OCA, and COS-7 monkey kidney cells." (PMID 19014669, 2008). "We found that overexpression of PTTG1 partially mitigated the negative influence of PTTG1-targeting miRNAs on the progression of pituitary tumor cells." (PMID 26320179, 2015).
pituitary adenomas (31 papers, 2006 to 2025). "Accordingly, it has been reported that PTTG1 cytoplasmic localization was more frequent in normal tissues and in pituitary adenomas, while the nuclear localization was associated with a more aggressive phenotype and to tumor recurrence." (PMID 33430117, 2021). "One work showed the significant association between PTTG1 and Ki-67 in pituitary adenomas, while the other studied the combination of Ki-67, Galectin-3, and PTTG to distinguish malignant forms of papillary or follicular thyroid cancer." (PMID 30911297, 2019). "In the majority of human GH-producing pituitary adenomas, p21-dependent senescence is associated with Pttg-1 overexpression." (PMID 26549306, 2015). "In the present study, we are the first to have investigated the association of individual PTTG1 SNPs or PTTG1 haplotypes with the risk of pituitary adenoma." (PMID 21439054, 2011). "To comprehensively study the genetic variants of PTTG1 associated with susceptibility to pituitary adenomas, we genotyped five PTTG1 haplotype-tagging SNPs (htSNP) using PCR-RFLP in a case-control study, which included 280 pairs of age-, gender- and geographically matched Han Chinese people." (PMID 21439054, 2011). "The expression of DLK1 and PTTG1 transcripts correlates with several normal and tumor tissues, including normal pituitary tissue and samples of pituitary adenoma or fetal liver and HCC." (PMID 35805898, 2022). "In normal tissues, PTTG1 is expressed at low levels with the only exception of testis, in which it is reported relatively higher than other tissues, but lower than pituitary adenomas." (PMID 33430117, 2021). "The E2F1-induced activation of CCAT2 enhances the interaction of CCAT2 with PTTG1 to promote the progression of pituitary adenomas." (PMID 34499007, 2021). "LncRNA CCAT2 was performed to interact with PTTG1 to promote pituitary adenoma cell proliferation, migration, and invasion, which further had an influence on human pituitary adenoma development and progression." (PMID 32192168, 2020). "Increased expression of PTTG1 has been extensively studied in pituitary adenomas, as well as a range of other endocrine cancers." (PMID 26445238, 2015). "Taken together, these results obtained from genetically modified mice indicate that PTTG1 facilitates pituitary adenoma formation." (PMID 25136513, 2014). "From the pathological point of view, PTTG1 has been found to be expressed at high levels in human pituitary adenomas and other malignant tumors including breast, lung, prostate, ovary and thyroid cancer, as well as in haematopoietic neoplasias." (PMID 18426563, 2008). "In a previous work, Kanakis and coworkers performed a sequencing scan in sixteen tumor biopsies from pituitary adenoma patients, searching for small deletion/insertion within those regions previously identified to be controlling PTTG1 expression." (PMID 18426563, 2008). "PTTG-1 (pituitary tumor transforming gene) is a novel oncogene that is overexpressed in tumors, such as pituitary adenoma, breast and gastrointestinal cancers as well as in leukemia." (PMID 16426442, 2006). "PTTG1 shows high expression in GH-secreting pituitary adenomas compared to healthy pituitary glands and regulates tumor-related metastasis and therapeutic responses, promoting cell migration and proliferation, as well as suppressing cell apoptosis, in several tumors." (PMID 35955787, 2022). "Conversely, miR-338-3p overexpression did not change GH mRNA and protein levels but increased Pituitary tumor-transforming gene 1 (Pttg1) expression, a proto-oncogene which is well known to be related with pituitary adenoma development, invasiveness and recurrence." (PMID 34484116, 2021). "While many studies are focused on exploring the PTTG1-mediated tumorigenic mechanisms, none was conducted to study the association of genetic alterations in PTTG1 with the risk of pituitary adenoma." (PMID 21439054, 2011).
pituitary adenomas (continued). "Although the expression levels of PTTG1 are restricted in normal cells, elevated expressions of PTTG1 were observed in many tumors including carcinomas of the lung, breast, colon, and ovary, leukemia and lymphoma, and also in pituitary adenomas." (PMID 19014669, 2008). "The oncogenic role of PTTG1 and HMGA2, two oncogenes previously suggested to play a relevant role in human pituitary adenoma formation, has been analyzed in transgenic mice." (PMID 25136513, 2014). "We genotyped five PTTG1 haplotype-tagging SNPs (htSNP) by PCR-RFLP assays in a case-control study, which included 280 Han Chinese patients diagnosed with pituitary adenoma and 280 age-, gender- and geographically matched Han Chinese controls." (PMID 21439054, 2011). "Accordingly, PTTG1 is highly expressed in endocrine and non-endocrine malignancies such as pituitary adenoma, astrocytoma, thyroid cancer, breast and ovarian cancer, renal cell carcinoma, lung cancer, colorectal carcinoma, HCC, and leukemia." (PMID 35805898, 2022). "This retrospective cohort study aimed to study the expression of tumoral biomarkers (CTSK, MMP9, MMP2, TIMP2, and PTTG1) and evaluate their clinical significance in non-functioning pituitary adenomas (NFPAs) with different invasion patterns." (PMID 36052250, 2022).